MET (MET proto-oncogene, receptor tyrosine kinase)
Diseases named in the same sentence as MET in open-access papers (continued):
Sharing a sentence is not in itself a finding about the gene and the disease.
tumor (continued). "As compared with ALDHlowCD44high non-stem tumor cells, increased enrichments of both p65 and BRD4 on SEs in both TP63 and MET were observed in ALDHhighCD44high CSCs." (PMID 34172737, 2021). "VEGF exerts a negative feedback on c-MET activation in a GBM mouse model, resulting in the direct suppression of tumor invasion." (PMID 32175278, 2020). "In the absence of HER3 ligands in cell culture, which are not endogenously produced by the tumor cells, this adaptive and rapid induction of HER3 did not confer resistance towards MET inhibition." (PMID 33374770, 2020). "Among other targetable tyrosine kinases AXL, MET and EGFR were expressed at high levels in some, but not all, tumor samples." (PMID 30881919, 2019). "Although, the majority of tumor samples showed no CNA of ALK, PDGFRA, VEGFR2/KDR, FGFR1, and to a lesser extent of MET in both primary and recurrent samples, the concordance of CNA status varied substantially in the subset of cases with alterations." (PMID 30894200, 2019). "Not surprisingly, ectopic expression of c-MET inhibits differentiation of stem-like GBM cells in a Nanog dependent manner, confirming the pivotal role of this kinase pathway for tumor stem cells." (PMID 29743557, 2018). "MetMab potently inhibited JHH5 but not MHCC97H tumor growth, which is consistent with the in vitro results that MetMab only inhibit HGF-dependent MET activation." (PMID 30208970, 2018). "There was a discrepancy between IHC and FISH results for tumor sample and GSC line 7 with no staining in IHC despite a high copy number of MET genes." (PMID 28960893, 2017). "TAS-115 at a dose of 200 mg/kg inhibited the phosphorylation of c-MET, AKT and ERK 1/2, while pazopanib did not affect c-MET signalling in Yamato-SS xenograft tumours." (PMID 28511645, 2017). "Collectively, SMAD3 did not bind to the promoter of MET to induce the expression of SNAIL, but rather, it regulated SNAIL in a direct way, which indicated the complexity of tumor progression." (PMID 28837140, 2017). "Among the 23 NSCLC patients with MET exon 14 skipping in our cohort, a 68 year-old non-smoker with MET, EGFR, and HER2 gene copy number gains in his tumor had relapsed." (PMID 27223439, 2016). "The c-MET and PIK3CA mRNA expression levels were independently significantly higher in tumor tissues compared with adjacent non-tumor tissues and these results were confirmed by IHC." (PMID 26334097, 2015). "As has been demonstrated in murine models, while HGF was secreted by HNSCC tumor-derived fibroblasts, but not by HNSCC cells, MET was expressed and functional in HNSCC cells." (PMID 26319934, 2015). "Animals treated with crizotinib alone had no statistically significant reduction in tumor size and showed no reduction in plasma PSA levels indicating that targeting c-MET alone is not sufficient." (PMID 25277255, 2014). "The mRNA levels for several critical components of the pathway (BIRC5, CD44, FZD7, c-MET, MMP7, c-MYC, NOTCH1, PPARD, and VEGF) were significantly increased (DASL signal intensity) in TN tumor samples as compared to non-TN tumor samples." (PMID 24143235, 2013). "A combined analysis of NSCLC, gastric, and HN tumor measurements did not reveal significant correlations between HGF/c-MET levels and c-MET expression (pearson r = 0.1782; p = 0.2063) or HGF expression (r = -0.021; p = 0.8794)." (PMID 21283737, 2011). "Tissue samples were obtained from tumor (TU), adjacent non-tumor (AN) and distant normal (DN) liver in Tet-operator regulated (TRE) human c-MET transgenic mice (n = 21) as well as from a Chinese cohort of 272 HBV- and 9 HCV-associated HCC patients." (PMID 21949730, 2011). "In the second case, RNA-based NGS performed on the recurrent tumor revealed a TRIM24::MET fusion between exon 12 of TRIM24 (NM_015905.2) and exon 15 of MET (NM_000245.3) and a gain of chromosome 7 without any evidence of further genetic alterations, especially no signs of CDKN2A/B deletion." (PMID 38902810, 2024).
tumor (continued). "Of note, the sensitivity of cell-free DNA assays at identifying and quantitating copy-number alterations can be low if there is low amount of tumor DNA present; in our case, the high VAFs of BRAF present suggest that lack of identification of MET amplification was not a false negative." (PMID 39626159, 2024). "Notably, in 11 patients with c-Met overexpression but without MET amplification, five SYK-positive patients exhibited significant tumor shrinkage after treatment with c-Metis." (PMID 37183231, 2023). "However, as HGF was found required for METex14‐dependent spheroid survival and tumour growth, these results indicate that some changes already occur with exon 14 splicing in the absence of HGF although they are not sufficient to drive MET oncogenicity." (PMID 36799689, 2023). "Interestingly, all the tumours displaying HGF expression had high METex14 expression (IHC2+ and IHC3+) but without MET or HGF gene amplification as determined by fluorescence in situ hybridisation of MET (FISH) and comparative genomic hybridisation (CGH)." (PMID 36799689, 2023). "However, circulating miR-155, miR-410, and miR-181a/b showed a negative correlation with tumor suppressive gene WNT5A (p < 0.0001, r = -0.671) and with oncogenes MET (p < 0.0001, r = -0.4778), EGFR (p < 0.0001, r = -0.5235, r = -0.5217)." (PMID 35646622, 2022). "One patient group contained MMs displaying MET overexpression (immunoscore 2+/3+ = MET-positive) with or without concomitant FISH-detected MET-GCNG/GA, while in the other group the tumor tissue was without MET overexpression (immunoscore 1+/0 and no MET-GCNG/GA = MET-negative)." (PMID 34884673, 2021). "As PSCs do not express the MET receptor, inhibition of the HGF/MET axis by the Combo treatment cannot directly influence the PSC status, but must be the consequence of a cross-talk between the tumor and the stroma compartment, which probably occurs through TNC." (PMID 34298732, 2021). "Cytokine profiling also confirmed the increased expression and secretion of proinflammatory cytokines in cells exposed to hypoxia and tumor xenografts treated with and without TMZ treatment, whereas the treatment with c-MET inhibitors significantly resolved the proinflammatory response." (PMID 33859738, 2021). "Interestingly, bioinformatic analysis of microarray data deposited in the GEO database revealed a positive correlation between MET and SNAIL expression in 158 RMS tumor samples derived from patients but not between SNAIL and CXCR4." (PMID 32664538, 2020). "Moreover, LY2801653 did not directly eradicate tumor cells that moderately express MET and AXL, but act on tumor microenvironment." (PMID 34766112, 2020). "However, amplification of EGFR, MET, and PIK3CA appear to be subclonal, in which all 3 oncogenes are coamplified within the same tumor cells as opposed to being each individually amplified across mutually exclusive clonal populations." (PMID 32338752, 2020). "The correlation between PD-L1 and MET was evaluated using the CCLE mRNA database, in order to determine whether the correlation was related to the intrinsic status of tumor and independent of the tumor microenvironment." (PMID 31480591, 2019). "For instance, a clinical study has shown that patients with MET-amplified esophagogastric cancer (EGC) develop resistance after about two months of MET inhibitor therapy, mainly due to the rapid growth of non-MET (EGFR or HER-2) amplified tumor cell subpopulations." (PMID 30849971, 2019). "However, in previous studies with c-MET inhibitors, combination with the Pi3k inhibitor Apitolisib or the MEK inhibitor Refametinib did not affect the anti-tumor efficacy of Tivantinib." (PMID 30850583, 2019).
tumor (continued). "In light of these considerations, therapies targeting the MET/HGF pathway in a context of expedience may impair the survival and the ability to disseminate of cancer cells, but are not expected to reduce tumor growth." (PMID 30544501, 2018). "Taken together, these results indicated that NZ001, a multitargeting RTK inhibitor that blocks both MET and VEGF signaling, has more significant inhibitory effect on tumor growth without inducing invasion and metastasis frequently observed after sorafenib treatment." (PMID 29712569, 2018). "However, with MET inhibitor PHA665752 treatment, the sh-CBL group not only showed more tumor inhibition than sh-control group but also showed no metastasis in the lung after treatment." (PMID 28835699, 2017). "No expression of CTNNB1, CTLA4, EPCAM, ERBB2, MET, p40, PD-L1 and SOX2 could be detected in any of the tumors, PD-L1 was negative in tumor as well as stromal cells." (PMID 26943575, 2016). "While studies have investigated MET expression in the primary clear cell RCC, no study to date has evaluated MET expression in a cohort of distant sites or compared matched primary tumor and metastases." (PMID 26448928, 2015). "In our model constitutive activation of MET signaling pathways blocked differentiation of the tumor cells in vivo, as TPR-MET tumors were formed by pleomorphic cells that did not shape into muscle fiber-like structures and were characterized by more undifferentiated morphology." (PMID 26384300, 2015). "However, this does not indicate that the cabozantinib inhibition of tumor growth does not involve VEGFR2 and MET signaling alterations." (PMID 24205338, 2013). "Importantly, targeted inhibition of EGFR and/or MET does not affect FER expression, suggesting that FER may sustain invasive tumor growth independently of specific GFR antagonism." (PMID 41115375, 2025). "However, the detection of HGF overexpression and MET activation without MET gene alterations is challenging because of the heterogeneity of HGF‐producing fibroblasts and instability of MET phosphorylation in tumor specimens." (PMID 36416133, 2023). "Thus, fusions in ROS1, RET, NTRK1 and amplifications in MET, ALK, EGFR, for example, may not be detected with circulating DNA and RNA, notably during tumor progression under treatment with TKI targeting ALK rearrangements." (PMID 33467720, 2021). "The finding that co-inhibition of MET and FGFR signalling reduces but does not completely abrogate sphere formation and tumour growth in human cell lines and PDXs may suggest the involvement of other compensatory pathways, such as EGFR, which has been associated with mesenchymal TNBCs88." (PMID 33772015, 2021). "Despite increased MET and RET expression in SCNPC, our results cumulatively suggest that cabozantinib acted through mouse endothelial VEGFR2 and inhibited angiogenesis leading to hypoxia and tumor cell death regardless of MET/RET status in both LuCaP SCNPC PDX models." (PMID 33471819, 2021). "We also determined that tumor-derived HGF, not systemic HGF, may be required to convey resistance to BRAF inhibition in vivo and that resistance could be reversed following treatment with AMG 337, a selective MET inhibitor." (PMID 28147313, 2017). "In addition, our observation of BsAb treatment was only limited to c-MET and PD-L1-positive tumor cells, however, we do not know whether BsAb has effects in c-MET and PD-L1-negative tumor cells." (PMID 28404966, 2017). "Patients harboring tumor genomic markers predicting poor outcomes to VEGF targeted therapy may be candidates for agents targeting primarily non-VEGF pathways, such as checkpoint inhibitors, c-MET inhibitors, a combination of VEGF-TKI plus checkpoint inhibitors, or clinical trials." (PMID 30682039, 2019).
cancer (2,079 papers, 2000 to 2026). A tumor composed of atypical neoplastic, often pleomorphic cells that invade other tissues. "Mutations within MET have been identified in a variety of cancers and have been shown to mediate tumorigenesis by increasing RTK activity and downstream signaling." (PMID 39858062, 2025). "The predominance of death is likely due to the MET exon 14 skipping mutation, which has been shown to be an independent prognostic factor for reduced survival in cancer patients." (PMID 41411333, 2025). "The c-MET pathway is often implicated in the development and progression of several types of cancers, including CRC." (PMID 40149618, 2025). "The juxtamembrane domain is encoded by exon 14 in MET, serves an incompletely understood negative regulatory function in the kinase and is recurrently excluded in cancer by somatically encoded exon skipping mutations." (PMID 39960754, 2025). "Focal MET gene amplification is the most common driver alteration for cancer, and it is recognized as the most common cause of osimertinib resistance." (PMID 40002158, 2025). "Aberrant activation of MET via gene amplification or mutations is a prominent feature of multiple human cancers." (PMID 41383124, 2025). "Collectively, these findings highlight the functional heterogeneity of MET mutations and their critical implications for therapeutic response in targeted cancer therapy." (PMID 40599602, 2025). "Dysregulation of the MET gene has been implicated in several diseases, including cancer and neurological disorders." (PMID 39129166, 2025). "The imbalance causes overactivation of HGF and leads to increased cancer cell proliferation, motility, and invasive activity through increased MET phosphorylation." (PMID 40299447, 2025). "Cancer-induced utilization of an alternative signaling pathway, the exon 14 skip mutation of MET, and mutation-induced MET amplification were considered as the mechanisms." (PMID 40299443, 2025). "Joffre reported that the presence of an activating mutation of MET in cancer cells would enhance oncogenic signal activity in the presence of HGF." (PMID 40299443, 2025). "Small-molecule inhibitors of MET have shown clinical efficacy in several human cancers, but resistance mutations often limit their durability." (PMID 41383124, 2025). "Targeting c-Met is a promising strategy, especially in cancers with MET gene amplification or mutations." (PMID 41348261, 2025). "HGF is a widely known CAF-secreted factor, and the HGF/MET-axis has often been found to be associated with cancer progression and the induction of therapy resistance." (PMID 40524253, 2025). "Determining the most effective inhibitor for each mutational profile is a major challenge for MET-driven cancer treatment in precision medicine." (PMID 39071407, 2024). "This success is the consequence of a long characterization of MET mutations in cancers, which we propose to outline in this review." (PMID 38652103, 2024). "c-MET, when deregulated, is associated with poor prognosis in many malignancies, while blocking PD-1 and PD-L1 interactions has shown promise in cancer immunotherapy." (PMID 39664377, 2024). "MET fusions, activating mutations, exon 14 skipping, and amplifications, leading to MET overexpression have been identified in a variety of human cancers." (PMID 38650040, 2024). "Human cancer development has been linked to the tyrosine kinase receptor MET, which is encoded by the MET gene to interact with the hepatocyte growth factor (HGF) to activate downstream pathways and promote cell proliferation, migration, and angiogenesis." (PMID 38893154, 2024). "The risk of cancer associated with the MET gene emerges when there is aberrant activation of its signaling pathways." (PMID 38675409, 2024). "For example, crizotinib and ceritinib (discussed in the ROS1/ALK section of this paper) have both demonstrated efficacy against MET-mutated cancers." (PMID 38339363, 2024).
cancer (continued). "CD24 and MET expression are associated with cancer malignancy and cancer stem‐like cell (CSC) features in various cancers." (PMID 38030594, 2024). "MET germline mutations have been linked to increased tumorigenicity in other cancers including colorectal." (PMID 38791602, 2024). "The first MET mutation was discovered in 1997, in hereditary papillary renal cancer (HPRC), providing the first direct link between MET mutations and cancer development." (PMID 38652103, 2024). "The MET proto-oncogene encodes the tyrosine kinase receptor for hepatocyte growth factor, which is often overexpressed in many human cancers." (PMID 39221422, 2024). "Another report demonstrates that cancer-associated fibroblast-derived IL-6 increased c-Met expression in MET-unamplified GC cells through the IL-6/IL-6R/JAK2/STAT3 signalling pathway." (PMID 37950040, 2024). "A novel BsAb was designed to target both PD-1 and c-MET, proteins implicated in cancer progression and immune response inhibition, respectively." (PMID 39664377, 2024). "Crizotinib, which is approved for the treatment of ALK- and ROS1-driven carcinomas, was historically developed as a MET inhibitor and, expectedly, demonstrated clinical activity towards MET-mutated carcinomas." (PMID 38966170, 2024). "The HGF/MET pathway is known to be associated with the appearance of several attributes of cancer and is utilized as a relevant target across many solid tumors." (PMID 37170275, 2023). "The association of c-MET with Wnt/β-catenin in particular has been demonstrated to promote cancer proliferation, progression, and metastasis." (PMID 36672275, 2023). "Other factors leading to drug resistance are cancer-associated fibroblasts secreting mitogenic growth factors that activate RAS or MET pathways, in addition to abnormal angiogenesis." (PMID 36979659, 2023). "When HGF binds to c-MET in cancer cells, they are stimulated to produce uPA, causing more pro-HGF to become active HGF, which then binds to c-MET in PC cells." (PMID 37173787, 2023). "New studies are ongoing to fine-tune our understanding of the role of varying MET mutations in cancer." (PMID 37760640, 2023). "Fittingly, PI3K/AKT activating mutations co-occur with MET Exon14 ‘skipping’ in 14% of cancer patients." (PMID 37760640, 2023). "Activation of MET is associated with many cancers, and several genes that are regulated by this signaling pathway are crucial for cancer initiation and progression." (PMID 37887325, 2023). "MET has been reported activated in some MPNSTs, and implicated in resistance to Ras pathway inhibition in several cancers, including melanoma and colorectal cancer." (PMID 37081086, 2023). "Oncogenic activation of receptor tyrosine kinases (RTKs) such as MET is associated with cancer initiation and progression." (PMID 37673888, 2023). "In HCC, the upregulation of the L1-MET transcript results in the accumulation of MET protein, which is associated with cancer metastasis and poor prognosis." (PMID 38136578, 2023). "Beyond this dysregulation, a variety of functionally similar genes associated with cancer progression were identified as upregulated in BAP1 KO MeT‐5A cells." (PMID 36740402, 2023). "Aberrant activation of the MET/HGF pathway has been found in many types of cancer and it is associated with disease progression, metastasis, and drug resistance." (PMID 37444518, 2023). "MET aberrations drive tumorigenesis in several cancer types through a variety of molecular mechanisms, including MET mutations, gene amplification, rearrangement, and overexpression." (PMID 36999986, 2023). "Aberrations in the HGF/MET pathway act as diagnostic, predictive, and prognostic biomarkers for cancers." (PMID 38022627, 2023). "Consistent with this possibility, there is substantial evidence for MET upregulation in association with advanced carcinoma treatment resistance." (PMID 37762668, 2023).